UCK2 (uridine-cytidine kinase 2)
Description:
Phosphorylates uridine and cytidine to uridine monophosphate and cytidine monophosphate. Does not phosphorylate deoxyribonucleosides or purine ribonucleosides. Can use ATP or GTP as a phosphate donor. Can also phosphorylate cytidine and uridine nucleoside analogs such as 6-azauridine, 5-fluorouridine, 4-thiouridine, 5-bromouridine, N(4)-acetylcytidine, N(4)-benzoylcytidine, 5-fluorocytidine, 2-thiocytidine, 5-methylcytidine, and N(4)- anisoylcytidine.
Synonyms: UMPK; TSA903; UK
Tractability: Small molecule: a structure with a bound ligand is known; it has a high-quality binding pocket. PROTAC: ubiquitination databases record sites on it; its protein half-life has been measured; a small molecule that binds it is known.
Target class: Enzyme; Transferase
Gene: Protein-coding gene on chromosome 1 (165,827,586 to 165,911,618, forward strand). Ensembl gene ENSG00000143179.
Subcellular location (Human Protein Atlas): Nucleoplasm; Cytosol
Pathways (Reactome):
Metabolism: Pyrimidine salvage
Gene Ontology:
Molecular function: cytidine kinase activity; identical protein binding; uridine kinase activity; ATP binding; kinase activity
Biological process: CTP salvage; UMP salvage; cellular response to oxygen levels; CMP biosynthetic process; feeding behavior; response to axon injury
Cellular component: cytosol
Genetic constraint (gnomAD): Loss-of-function variants: 6 observed, 28.12 expected, observed/expected ratio (o/e) 0.21, 90% interval 0.12 to 0.42. The upper end of that interval is the gene's LOEUF score, 0.42, which puts it in group 1 of 6, group 1 being the genes least tolerant of losing a copy. Missense variants: 210 observed, 328.02 expected, observed/expected ratio (o/e) 0.64, 90% interval 0.57 to 0.72. Synonymous variants: 125 observed, 128.98 expected, observed/expected ratio (o/e) 0.97, 90% interval 0.84 to 1.12.
Homologues: Orthologues: chimpanzee UCK2 (100% identical), macaque UCK2 (100% identical), guinea pig UCK2 (99% identical), pig UCK2 (99% identical), mouse Uck2 (98% identical), dog UCK2 (97% identical), rat Uck2 (89% identical), rabbit UCK2 (87% identical), tropical clawed frog uck2 (85% identical), zebrafish uck2a (84% identical), zebrafish uck2b (79% identical), Drosophila melanogaster Uck (61% identical), and 1 more. Paralogues in human: UCK1 (72% identical), UCKL1 (49% identical), UPRT (10% identical).
Diseases named in the same sentence as UCK2 in open-access papers:
UCK2 is named in the same sentence as 37 diseases in open-access papers, as found by Europe PMC text mining. Sharing a sentence is not in itself a finding about the gene and the disease. The quoted sentences say what the papers report.
lung carcinoma (15 papers, 2016 to 2025). "Recent studies have shown that UCK2 is overexpressed in many types of solid and hematopoietic cancers, closely associates with poor prognosis, and promotes cell proliferation and migration in lung cancer and HCCs." (PMID 35669416, 2022). "Similarly, the Kaplan-Meier survival analysis showed that pyrimidine metabolic rate–limiting enzymes DTYMK, NT5C3, RRM1, RRM2, TK1, TYMS, and UCK2 were all associated with adverse prognosis in the lung cancer." (PMID 32638267, 2020). "UCK2 was proved to promote migration and invasion of hepatocellular carcinoma cells, which was also seen to be a latent diagnostic and prognostic indicator for lung cancer." (PMID 32699528, 2020). "The expression of UCK2 is elevated in various cancer tissues, including breast cancer, hepatocellular carcinoma, lung cancer, it is considered a prognostic biomarker for these cancers." (PMID 39931080, 2025). "UCK2 expression was positively associated with poor overall survival in HCC, pancreatic cancer, and lung cancer." (PMID 39179560, 2024). "UCK2 is reported to be a carcinogenic factor in many malignancies, including lung cancer, pancreatic cancer and breast cancer." (PMID 38245591, 2024). "UCK2 upregulation has been reported in several types of cancers including lung cancer, breast cancer, neuroblastoma, colorectal cancer, pancreatic cancer, and HCC." (PMID 39179560, 2024). "Specifically, a high expression level of UCK2 has also been identified in stage IA lung cancer related to early recurrence, poor first progression survival, and short overall survival." (PMID 34595103, 2021). "And the pyrimidine metabolic rate–limiting enzymes DTYMK, NT5C3, RRM1, RRM2, TK1, TYMS, and UCK2 had particular values in lung cancer prognosis." (PMID 32638267, 2020). "Some of the pyrimidine metabolic rate–limiting enzymes, such as TK1, UCK2, and RRM1, were reported to be associated with the poor outcomes of lung cancer in systematic review or meta-analysis." (PMID 32638267, 2020). "We showed that 6% lung cancer patients were with UCK2 amplification and 5% lung cancer patients were with UCKL1 amplification." (PMID 32638267, 2020). "A prior study on lung cancer has indicated a correlation between UCK2 and DNA repair." (PMID 39931080, 2025). "UCK2 has been proven to enhance the migration and invasion of HCC cells, which was also identified to be a latent diagnostic as well as a prognostic indicator for lung cancer and breast cancer." (PMID 37999212, 2023). "Moreover, functional studies have demonstrated that overexpression of UCK2 can promote cell proliferation and migration in lung cancer and HCCs." (PMID 35669416, 2022). "UCK2 may be a biomarker for early diagnosis and prognosis of lung cancer." (PMID 32457792, 2020). "Further, UCK2 was upregulated and played as an oncogenic role in HCC, pancreatic cancer, lung cancer, testicular germ cell tumors and endometrial cancer." (PMID 39179560, 2024). "Overexpression of UCK2 is regarded as an indicator of unfavorable prognosis in various cancers, including HCC, pancreatic cancer, breast cancer, and lung cancer." (PMID 32670881, 2020).
hepatocellular carcinoma (14 papers, 2020 to 2026). A malignant tumor that arises from hepatocytes. "Studies have shown that in hepatocellular carcinoma, down-regulation of UCK2 induces cell cycle arrest and activates the age-related secretory phenotype associated with the TNF-α NFκB signaling pathway to alter the tumor microenvironment." (PMID 39931080, 2025). "By targeting UCK2, the progression of hepatocellular carcinoma can be inhibited, potentially leading to improved response to immunotherapy in patients with this disease." (PMID 39931080, 2025). "According to reports, UCK2 genes has been found to enhance the immune response in cases of hepatocellular carcinoma." (PMID 39931080, 2025). "Uridine–cytidine kinase 2 (UCK2), a key regulator of pyrimidine metabolism, is elevated during hepatocellular carcinoma (HCC) development and exhibits carcinogenic effects." (PMID 36447138, 2022). "A number of studies reported that SEMA3F, UCK2, NOL10, RAP2A, ZIC2 and SAC3D1 are associated with prognosis and tumour immune infiltration in hepatocellular carcinomas." (PMID 34760691, 2021). "As a key enzyme involved in nucleotide synthesis during DNA replication, UCK2 overexpression may drive abnormal hepatoma cell proliferation." (PMID 41357200, 2025). "UCK2, a type of rate-limiting enzyme of pyrimidine-nucleotide biosynthesis, is detected to up-regulate in several types of tumors, including neuroblastoma and hepatocellular carcinoma." (PMID 34595103, 2021). "In hypoxic hepatocellular carcinoma (HCC), NEAT1 sponges miR-199a-3p to promote cell proliferation by increasing the expression of UCK2." (PMID 35625948, 2022). "Uridine-cytidine kinase 2(UCK2) was positively correlated with early recurrence and poor prognosis in hepatocellular carcinoma." (PMID 32894095, 2020). "Overexpression of UCK2 increased MMP2/9 expression and further activated Stat3 signaling, mediating the metastasis of hepatocellular carcinoma cells." (PMID 32894095, 2020). "Moreover, the potential regulatory mechanism of circUCK2 related to miR-149-5p and UCK2 in hepatocellular carcinoma malignant progression was investigated, which might provide additional strategies for HCC therapy." (PMID 38245591, 2024).
breast carcinoma (6 papers, 2018 to 2024). "For instance, UCK2 was upregulated in breast cancer, and elevated UCK2 expression was related to poor prognosis." (PMID 38245591, 2024). "Overexpression of UCK2 was exhibited to be correlated with breast cancer progression and worse prognosis." (PMID 32699528, 2020). "This gene has previously been reported to be upregulated in a few dup(1q)-positive HeH cases, and overexpression of UCK2 was recently shown to correlate with progression/poor prognosis in breast cancer." (PMID 29626196, 2018). "UCK2 has also been recognized as an indicator of unfavourable prognosis in HCC and breast cancer, which was similar to our result." (PMID 34423480, 2021).
melanoma (5 papers, 2021 to 2025). A malignant, usually aggressive tumor composed of atypical, neoplastic melanocytes. "Among these regulators, METTL3 modulates the migratory capabilities of melanoma cells, specifically by modifying the RNA m6A of UCK2." (PMID 39247584, 2024). "Moreover, AR extract can reduce the m6A level of the key UCK2 in melanoma cell migration and reduce its mRNA level." (PMID 39247584, 2024). "In addition, UCK2 enhanced the migration and invasion ability of melanoma cells by activating the Wnt/β-catenin pathway." (PMID 37124930, 2023). "METTL3 could modulate the mRNA level of uridine cytidine kinase 2 (UCK2) through m6A modification to enhance its stability in melanoma." (PMID 37124930, 2023). "In melanoma, METTL3-mediated stabilization of the uridine cytidine kinase 2 (UCK2) by m6A modification plays a role in melanoma metastasis by enhancing the Wnt/β-catenin pathway." (PMID 37369946, 2023). "Downregulated molecules include MMP2 and N-cadherin, both of which are necessary for melanoma metastasis and invasion, TXNDC5, which increases cell proliferation potential, and UCK2, which enhances melanoma cell migration via the Wnt/β-catenin signaling pathway." (PMID 41157107, 2025).
prostate carcinoma (5 papers, 2017 to 2023). A carcinoma that arises from epithelial cells of the prostate gland. "As another example, the circRNA UCK2 simultaneously inhibits invasion and enzalutamide resistance by upregulating TET1 in prostate cancer." (PMID 32799866, 2020).
liver cancer (4 papers, 2021 to 2025). An epithelial or non-epithelial malignant neoplasm that arises from the liver. "For the study of cancer cell stemness, the gene UCK2 was mentioned in a nine-gene-based stemness classifier prediction model designed to predict immunotherapy response and prognosis of liver cancer." (PMID 39931080, 2025). "Recently, only in liver cancer, the interaction between gene UCK2 and immunity has been studied more, and other cancers have been involved less." (PMID 39931080, 2025).
pancreatic cancer (4 papers, 2019 to 2024). "What’s more, UCK2 could serve as a prospective biomarker of potential response to RX-3117 treatment in pancreatic cancer patients." (PMID 39179560, 2024).
colon cancer (3 papers, 2016 to 2025). "The current investigation provided insight to the isolated compounds, FKB and APN as potential UCK2 inhibitors for future treatment of colon cancer." (PMID 28103302, 2017). "Human placenta indeed showed a high expression of UCK2 as well as samples from human liver metastases derived from colon cancer." (PMID 27612203, 2016).
lung adenocarcinoma (3 papers, 2016 to 2026). A carcinoma that arises from the lung and is characterized by the presence of malignant glandular epithelial cells. "Overlapping genes, including XCT and UCK2, are adverse prognostic factors of lung adenocarcinoma, and the mechanism may be related to regulating the cell cycle of cancer cells." (PMID 33619234, 2021).
lymphoma (3 papers, 2023 to 2024). A malignant (clonal) proliferation of B- lymphocytes or T- lymphocytes which involves the lymph nodes, bone marrow and/or extranodal sites. "For example, MPZL1 and UCK2 loci uniformly hypermethylated in normal T-cells were hypomethylated in lymphomas with high frequency." (PMID 38464090, 2024). "In other studies, UCK2 was downregulated in AZA-resistant AML cell variants at the mRNA level or at the protein level in AZA-resistant cells from histiocytic lymphoma, AML, and adult T-cell leukemia-lymphoma." (PMID 37297025, 2023).
colorectal cancer (2 papers, 2017 to 2022). A primary or metastatic malignant neoplasm that affects the colon or rectum. "We therefore tend to investigate further the mechanism by which FKB and APN inhibit growth of colorectal cancer through inhibition of UCK2 enzyme in human HT-29 cells." (PMID 28103302, 2017). "The present study was carried out to demonstrate the potentials of natural phytochemicals from the rhizome of Alpinia mutica to inhibit UCK2 useful for colorectal cancer." (PMID 28103302, 2017). "For example, direct UCK2 inhibition induced cell death in colorectal cancer cells by reducing 18S RNA expression and led to subsequent cell cycle arrest, suggesting that UCK2 inhibition could impair RNA biosynthesis." (PMID 35669416, 2022).
endometrial cancer (2 papers, 2024 to 2025). Primary or metastatic malignant neoplasm involving the endometrium (mucous membrane that lines the endometrial cavity). "We found that the expression of UCK2 was highly expressed in cancer tissue disease compared to normal tissue, for example, BRCA, COAD, PRAD, OV, BLCA, Endometrial cancer (EC), PAAD, READ, STAD, LUAD, and Cervical squamous cell carcinoma (CSCC)." (PMID 39931080, 2025).
heart failure (2 papers, 2025). Inability of the heart to pump blood at an adequate rate to meet tissue metabolic requirements. "Recent studies have also shown that UCK2 is an important gene related to heart failure." (PMID 39931080, 2025). "Given that maladaptive fibrosis is a principal determinant of heart failure following myocardial infarction, targeting the UCK2/UCKL1-TRIM21 regulatory node offers a promising therapeutic strategy to arrest fibrogenesis and improve clinical outcomes in ischemic heart disease." (PMID 41457201, 2025). "Cardiac fibroblasts are the most important cells mediating the occurrence of myocardial fibrosis, UCK2 is highly expressed in fibroblasts, and inhibition of UCK2 expression may slow down or even reverse heart failure." (PMID 39931080, 2025). "UCK2 may be an important target for reversing heart failure." (PMID 39931080, 2025).
leukemia (2 papers, 2020 to 2021). A malignant (clonal) hematologic disorder, involving hematopoietic stem cells and characterized by the presence of primitive or atypical myeloid or lymphoid cells in the bone marrow and the blood. "To better understand contributions of DCK and UCK2 to dCTP and dTTP maintenance, we knocked DCK and UCK2 out of leukemia cells (HAP1) using CRISPR-Cas9 then measured levels of the deoxynucleotides." (PMID 32770088, 2021). "Therefore, we performed additional in vitro experiments based on the two best 5-protein models (which shared TYMP, RRM1, UPP1, and UCK1 and contained either PPAT or UCK2) using two CRC and two leukemia cell lines that are predicted to be sensitive or resistant to 5FU." (PMID 32686665, 2020).
ovarian carcinoma (2 papers, 2016 to 2023). A malignant neoplasm originating from the surface ovarian epithelium. "Further dependencies were identified for this complex within specific histotypes including the uridine-cytidine kinase gene UCK2 in ovarian cancer models and the death-associated protein kinase gene DAPK1 in esophageal cancer models." (PMID 26947069, 2016).
bladder cancer (1 paper, 2025). "The mutation status of UCK2 in various cancers was evaluated and is depicted in, we found that high UCK2 amplification in most cancers, especially cholangiocarcinoma, bladder cancer." (PMID 39931080, 2025).
head and neck cancer (1 paper, 2020). A primary or metastatic malignant neoplasm affecting the head and neck. "This may partially explain the failure of a clinical trial of nucleoside 3′-C-ethynylcytidine (TAS-106), a cytidine analogue subjected to UCK2 phosphorylation, in treatment of head and neck cancer and nasopharyngeal cancer." (PMID 33277463, 2020).
inflammatory bowel disease (1 paper, 2018). A spectrum of small and large bowel inflammatory diseases of unknown etiology. "Along with those already mentioned, other top up-regulated DEGs such as Uck2, Krt23, Pcsk9, and S100a11 have also been associated with cancer or inflammatory bowel disease (IBD), likely reflecting their roles in cell proliferation or repair." (PMID 29339782, 2018).
metastasis (1 paper, 2024). The spread or migration of cancer cells from one part of the body (where they first appeared) to another. "UCK2 expression was positively correlated with lymph node metastasis (P < 0.05), vascular invasion (P < 0.05) and large tumor size (P < 0.05)." (PMID 39179560, 2024).
myelodysplastic syndrome (1 paper, 2016). A clonal hematopoietic disorder characterized by dysplasia and ineffective hematopoiesis in one or more of the hematopoietic cell lines. "A lower UCK1 expression for myelodysplastic syndrome (MDS) patients has been associated with reduced survival rate, while point mutations in UCK2 have been found in human leukemic cell lines made resistant to Aza-CR." (PMID 27612203, 2016).
myocardial infarction (1 paper, 2025). Gross necrosis of the myocardium, as a result of interruption of the blood supply to the area, as in coronary thrombosis. "In a murine model of myocardial infarction (MI), individual knockdown of either UCK2 or UCKL1 significantly ameliorated pathological remodeling, evidenced by preserved cardiac function, attenuated hypertrophy, and reduced pulmonary edema." (PMID 41457201, 2025).